DPP10 (dipeptidyl peptidase like 10)
Description:
Promotes cell surface expression of the potassium channel KCND2. Modulates the activity and gating characteristics of the potassium channel KCND2. Has no dipeptidyl aminopeptidase activity.
Synonyms: DPRP-3; DPL2; DPRP3; DPPY
Tractability: Small molecule: it belongs to a druggable protein family. Antibody: UniProt places it where antibodies can reach, with high confidence; UniProt predicts a signal peptide or a membrane-spanning region; its Gene Ontology location is reachable by antibodies, with medium confidence. PROTAC: its protein half-life has been measured.
Gene: Protein-coding gene on chromosome 2 (114,442,299 to 115,845,780, forward strand). Ensembl gene ENSG00000175497.
Subcellular location: Cell membrane
Gene Ontology:
Molecular function: dipeptidyl-peptidase activity; transmembrane transporter binding; potassium channel regulator activity; serine-type peptidase activity
Biological process: positive regulation of protein localization to plasma membrane; protein localization to plasma membrane; regulation of potassium ion transmembrane transport; proteolysis
Cellular component: membrane; plasma membrane; voltage-gated potassium channel complex
Genetic constraint (gnomAD): Loss-of-function variants: 23 observed, 86.29 expected, observed/expected ratio (o/e) 0.27, 90% interval 0.19 to 0.38. The upper end of that interval is the gene's LOEUF score, 0.38, which puts it in group 1 of 6, group 1 being the genes least tolerant of losing a copy. Missense variants: 630 observed, 760.55 expected, observed/expected ratio (o/e) 0.83, 90% interval 0.77 to 0.88. Synonymous variants: 276 observed, 268.74 expected, observed/expected ratio (o/e) 1.03, 90% interval 0.93 to 1.13.
Homologues: Orthologues: chimpanzee DPP10 (98% identical), macaque DPP10 (97% identical), dog DPP10 (94% identical), pig DPP10 (93% identical), rabbit DPP10 (92% identical), guinea pig DPP10 (91% identical), rat Dpp10 (88% identical), mouse Dpp10 (88% identical), Drosophila melanogaster CG3744 (20% identical), Caenorhabditis elegans dpf-3 (16% identical). Paralogues in human: DPP6 (52% identical), DPP4 (32% identical), FAP (32% identical), DPP9 (24% identical), DPP8 (22% identical), APEH (15% identical).
Diseases named in the same sentence as DPP10 in open-access papers:
DPP10 is named in the same sentence as 55 diseases in open-access papers, as found by Europe PMC text mining. Sharing a sentence is not in itself a finding about the gene and the disease. The quoted sentences say what the papers report.
asthma (26 papers, 2005 to 2026). "The human DPP10 gene was identified as a candidate gene for the prognosis of susceptibility to asthma, a common disease of the airways involving atopic inflammation and hyper-responsiveness to various agents." (PMID 37511372, 2023). "The association of DPP10 with asthma has been confirmed across several different ethnic populations." (PMID 29361513, 2018). "To date, DPP10 is the only gene found to show asthma association by both positional cloning and genome-wide association studies (GWAS)." (PMID 29361513, 2018). "Here, we report the establishment of a novel mouse mutant carrying a DPP10 point mutation and its effects on experimental asthma." (PMID 29361513, 2018). "We previously identified dipeptidylpeptidase 10 (DPP10) on chromosome 2 as a human asthma susceptibility gene, through positional cloning." (PMID 29361513, 2018). "Previously, we have established that polymorphisms in DPP10 on human chromosome 2 were associated with asthma traits through positional cloning." (PMID 29361513, 2018). "Our data provide functional experimental evidence supporting previous human genetic data indicating that DPP10 is an asthma susceptibility gene." (PMID 29361513, 2018). "Among the top 160 SNPs, one SNP (rs10496476) is located within the intron of gene DPP10, which has been shown to be associated with asthma in multiple populations, based on a recent review." (PMID 21718536, 2011). "Although evidence showed that childhood and adult asthma differed in several parameters, the associations between PHF11, DPP10, HLA-G and asthma or asthma-related phenotypes were found in both groups." (PMID 19951440, 2009). "Our results confirm previous associations of DPP10 and asthma or asthma-related phenotype, but differ in the details." (PMID 19951440, 2009). "Associations between SNPs in PHF11, DPP10, HLA-G and asthma or asthma-related phenotypes, adjusted for age, gender, height, weight, BMI and smoking status." (PMID 19951440, 2009). "Associations between haplotypes in PFH11, DPP10, HLA-G and asthma-related phenotypes, adjusted for age, gender, height, weight, BMI and smoking status." (PMID 19951440, 2009). "In this article, we examined the associations of polymorphisms in the identified top regions of PHF11, DPP10, and HLA-G with asthma and asthma-related phenotypes in a Chinese population, using a population-based study design." (PMID 19951440, 2009). "Our study provides supportive evidence to the previously reported associations between the DPP10 gene and asthma or asthma-related phenotypes in Caucasian populations." (PMID 19951440, 2009). "To date, DPP10 was identified to be associated with asthma and lung function." (PMID 41340014, 2025). "The gene DPP10 has been associated with asthma in prior studies." (PMID 37242299, 2023). "Moreover, DPP10 polymorphisms have been linked to asthma and knockdown of DPP10 in bronchial epithelial cells altered responses to IL-1 stimulation." (PMID 33424831, 2020). "Initial association results were confirmed in many subsequent association studies but the functional role of DPP10 in asthma remains unclear." (PMID 29361513, 2018). "These suggest other potential mechanisms for DPP10 association with asthma." (PMID 27658857, 2016). "DPP10 has also been linked to asthma by several association studies of linkage and fine mapping." (PMID 20485525, 2010). "Although DPP10 has been associated with asthma in both genome-wide and wet-laboratory studies, its functional role in asthma is almost completely unknown, due in large part to the absence of any genetic models." (PMID 29361513, 2018). "Interestingly, rare structural variants of DPP10 confer strong genetic susceptibility to autism, while some of the gene's more common variants contribute to a significant risk for bipolar disorder, schizophrenia, and asthma." (PMID 23185133, 2012).
asthma (continued). "While DPP10 and HDAC9 were implicated as risk loci for asthma susceptibility and/or severity and related phenotypes, this study is the first to indicate an association of these genes with ICS response." (PMID 32119686, 2020). "Other asthma-associated genes with possible roles in barrier function are DPP10 (dipeptidyl peptidase 10) and GPRA (G protein–coupled receptor for asthma susceptibility)." (PMID 33255348, 2020). "In order to investigate the possible functional roles of DPP10 in human lungs, we also investigated DPP10 expression in asthma patients." (PMID 29361513, 2018). "Further SNPs in DPP10, IL12B and IL4 were now found to be associated with asthma in our population, but only at the nominal significance level of 0.05." (PMID 21103062, 2010). "Our study is the first one to provide additional evidence that supports the roles of DPP10 in influencing asthma or BHR in a Chinese population." (PMID 19951440, 2009). "Note that L1 contains a significant candidate region of 60891 bp closed to an asthma-suspected gene DPP10 with functions of catalytic activity and dipetidyl-peptidase IV activity." (PMID 18503718, 2008). "Region 2p12-q22.1 contains the DPP10 gene that has previously been identified as an asthma and total IgE susceptibility gene and the IL1RN gene identified using asthma as the primary phenotype." (PMID 18442398, 2008). "We report that THSD4, HIVEP2, DPP10, HDAC9 and other genes within inflammatory response pathways and with definitive roles in asthma susceptibility, severity, and exacerbations, are also asthma pharmacogenes." (PMID 32119686, 2020). "In addition to THSD4 and HIVEP2, age-by-genotype interactions also prioritized genes previously identified as asthma candidate genes, including DPP10, HDAC9, TBXAS1, FBXL7, and GSDMB/ORMDL3, as pharmacogenomic loci as well." (PMID 32119686, 2020). "Results from both murine and human in vivo and in vitro analyses suggest that DPP10 might play a protective role in asthma." (PMID 29361513, 2018). "Considering the important role of potassium ion channels in asthma, DPP10 may also be involved in this process although this requires further investigation." (PMID 27658857, 2016). "Although asthma is the complex disease with the largest number of genome scans (currently more than 15 studies), few genes have been associated with the disease (as far as we know; those are ADAM33, DPP10, PHF11, GPRA, and Vitamin D receptor)." (PMID 16115313, 2005). "Our data provide evidence that DPP10 might play a protective role in asthma." (PMID 29361513, 2018). "We found that DPP10 was significantly associated with bronchial hyperresponsiveness (BHR) and BHR asthma after the adjustment for multiple testing; while the associations of PHF11 with positive skin reactions to antigens and the associations of HLA-G with BHR asthma were only nominally significant." (PMID 19951440, 2009). "Six asthma candidate genes, ADAM33, NPSR1, PHF11, DPP10, HLA-G, and CYFIP2, located at different chromosome regions have been positionally cloned following the reported linkage studies." (PMID 19951440, 2009). "This indicates that DPP10 may be important in neural regulation of airway smooth muscle and control of airway reactivity, which may explain our finding that the haplotype containing the SNP rs10192393 in DPP10, 4 kb upstream of D2S308, was associated with BHR and BHR asthma." (PMID 19951440, 2009). "DPP10 is a potassium channel-associated protein, but unlike other DPP family members, mammalian DPP10 lacks enzymatic activity and is unable to cleave terminal dipeptides from asthma-related cytokines and chemokines." (PMID 29361513, 2018).
autism (5 papers, 2011 to 2025). Persistent deficits in social interaction and communication and interaction as well as a markedly restricted repertoire of activity and interest as well as repetitive patterns of behavior. "Repeatedly, studies have shown that autistic individuals have deletions in synaptic genes, such as SHANK3, dipeptidyl peptidase-like 10 (DPP10), neuroligins, and neurexins." (PMID 31481879, 2019). "Three loci, including DPP10 on chromosome 2q14.1 and two genes in close proximity on chromosome 3p26.3, CNTN4 and CHL1, both encoding cell adhesion molecules, confer very strong susceptibility to autism, schizophrenia, and related disease." (PMID 23185133, 2012).
Alzheimer disease (3 papers, 2018 to 2025). A progressive, neurodegenerative disease characterized by loss of function and death of nerve cells in several areas of the brain leading to loss of cognitive function such as memory and language. "In the brain, DPP10 malfunction is associated with neurodegenerative conditions such as Alzheimer’s disease and frontotemporal lobe dementia." (PMID 29361513, 2018). "Abnormal expression of DPP10 in the neurofibrillary tangles and plaque‐associated dystrophic neurites of the human brain has been associated with neurodegenerative disorders such as Alzheimer's Disease and other major tauopathies (Chen, Gai, and Abbott 2014)." (PMID 39954235, 2025). "DPP10 has been linked to ADHD and neurodegenerative processes in Parkinson’s and Alzheimer’s diseases." (PMID 29997484, 2018).
autism spectrum disorder (3 papers, 2017 to 2020). A spectrum of developmental disorders that includes autism, and Asperger syndrome. "In some cases, copy imbalances at the 3′ end can be benign, such as duplications of the DPP10 gene in autism spectrum disorders." (PMID 33584815, 2020). "In addition, a significant enrichment among the nominal DEGs for genes implicated in autism spectrum disorder (ASD) was found (e.g., AFF2, DNER, DPP6, DPP10, RELN, CACNA1C), as well as several that are strong candidate genes for the development of eye problems found in LS, including glaucoma." (PMID 32393163, 2020).
breast carcinoma (2 papers, 2013 to 2021). "In parallel studies for downregulated genes, we were able to identify seven genes with mutations in colon cancer (DPP10, PCSK2, ADAM33, RELN, CAPN13, ADAMTS1 and ADAMTS15), and five genes with mutations in breast carcinomas (MASP3, ABHD12B, TLL1, CPA3 and DPP6)." (PMID 24243807, 2013). "Data demonstrated that DPP3, DPP7, DPP8, DPP9, and DPP10 mostly had medium protein expression levels, while some clinical tissues showed strong positive expression levels of DPP3, DPP7, and DPP9 in breast cancer specimens." (PMID 34359286, 2021). "This family comprises seven members, including DPP3, DPP4, DPP6, DPP7, DPP8, DPP9, and DPP10; however, information on the involvement of DPPs in breast cancer is lacking in the literature." (PMID 34359286, 2021).
lung squamous cell carcinoma (2 papers, 2021 to 2025). "Our study highlights an association between DPP10 and a higher risk of lung squamous cell carcinoma, as evidenced by findings from a cohort study, MR analyses and bulk transcriptomic analyses." (PMID 41340014, 2025). "DPP10 could be a novel therapeutic target, offering a new avenue for lung squamous cell carcinoma therapy." (PMID 41340014, 2025). "Interestingly, the DPP10 methylation level in lung squamous cell carcinoma was significantly lower than that in healthy controls from the MethHC methylation database." (PMID 34106559, 2021). "However, the function and mechanism of DPP10 in lung squamous cell carcinoma remain unclear." (PMID 41340014, 2025).
schizophrenia (2 papers, 2012 to 2023). A major psychotic disorder characterized by abnormalities in the perception or expression of reality. "Seven switch genes, NPAS3, ARHGAP15, LGALS3BP, DPP10, SMYD3, CPXCR1, and HLA-DRB5, were associated with known risk factors for schizophrenia." (PMID 36982982, 2023). "Likewise, NPAS3, ARHGAP15, LGALS3BP, DPP10, SMYD3, CPXCR1, and HLA-DRB5 were associated with known risk factors for schizophrenia." (PMID 36982982, 2023).
colitis (1 paper, 2022). Inflammation of the colon. "These candidate biomarkers, MST1L, OLFM4, and DPP10, were predicted to be strongly associated with immune cell infiltration of colitis, especially γδ T cells, neutrophils, and macrophages M1." (PMID 34939750, 2022). "To further confirm the differential expression of these candidate genes between ulcerative colitis and normal groups, we determined the mRNA expression of SGK1, CEP55, ACSL1, OLFM4, MGP, and DPP10 in colon tissues of DSS‐induced colitis mice." (PMID 34939750, 2022). "We also examined SGK1, CEP55, ACSL1, OLFM4, DPP10, and MGP expression in the colon tissues of dextran sodium sulfate‐induced colitis mice." (PMID 34939750, 2022). "In addition, we also examined the expression of SGK1, CEP55, ACSL1, OLFM4, DPP10, and MGP in the colon tissues of DSS‐induced colitis mice." (PMID 34939750, 2022). "In addition, we also examined the expression of SGK1, CEP55, ACSL1, OLFM4, DPP10, and MGP in the colon tissues of dextran sulfate sodium‐induced colitis mice." (PMID 34939750, 2022).
early repolarization syndrome (1 paper, 2022). "DPP10 has been reported to be associated with heritable fatal severe pediatric J-wave syndromes such as BrS and early repolarization syndrome." (PMID 36274122, 2022).
epilepsy (1 paper, 2022). A brain disorder characterized by episodes of abnormally increased neuronal discharge resulting in transient episodes of sensory or motor neurological dysfunction, or psychic dysfunction. "Many of these genes are associated with epilepsy and ictogenesis, including DPP10, DOCK8, IAH1, LRRC4C, and SLC6A5." (PMID 36506088, 2022). "DPP10 interacts with the voltage-gated K+ channel 4 (Kv4), whose dysfunction has been associated with epilepsy and ASD with concomitant epilepsy." (PMID 36506088, 2022). "DPP10 dysregulation could through control of Kv4.2 function, contribute to auditory hypersensitivity, auditory startle, and the epilepsy phenotype in FXS." (PMID 36506088, 2022).
fronto-temporal dementia (1 paper, 2015). "As a consequence, DPP10 malfunctioning is associated with neurodegenerative conditions like Alzheimer and fronto-temporal dementia, making this protein an attractive drug target." (PMID 25740212, 2015).
glioblastoma (1 paper, 2021). The most malignant astrocytic tumor (WHO grade IV). "DPP10 was underexpressed in primary glioblastomas, and was also found to be down-expressed in nasopharyngeal carcinoma." (PMID 34359286, 2021).
idiopathic intracranial hypertension (1 paper, 2024). "We found a significant difference between the two groups, in which genes such as CLEC2A, TBC1D3, and DPP10 were upregulated in the group of idiopathic intracranial hypertension." (PMID 39605979, 2024).
influenza (1 paper, 2024). An acute viral infection of the respiratory tract, occurring in isolated cases, in epidemics, or in pandemics; it is caused by serologically different strains of viruses (influenzaviruses) designated A, B, and C, has a 3-day incubation period, and usually lasts for 3 to 10 days. "With few exceptions (for example, DPP10 with influenza), protective proteins were decreased among individuals with a prior infection, whereas pathogenic proteins were increased." (PMID 39143319, 2024).
leukemia (1 paper, 2025). A malignant (clonal) hematologic disorder, involving hematopoietic stem cells and characterized by the presence of primitive or atypical myeloid or lymphoid cells in the bone marrow and the blood. "As expected, several previously reported genes with abnormal methylation in leukemias such as CPEB1, BLK, FLT3, ZCCHC7, EBF1, HDACs, IKZF1, RB1, CDK6, DOCK5, DPP10, MUC4, JAKs, KIT, KRAS, LINC01013, MAD1L1, NOTCH1, and STATs, among others, were also detected." (PMID 41226303, 2025).
major depression (1 paper, 2024). "Nevertheless, some other relevant overexpressed genes detected after CASh analysis of the major depression datasets include EXOSC2 (Exosome Component 2), DPP10 (Dipeptidyl Peptidase Like 10), GSTM5 (Glutathione S-Transferase Mu 5), and ZNF184 (Zinc Finger Protein 184)." (PMID 39727940, 2024).
pulmonary diseases (1 paper, 2026). "This narrative review summarizes recent clinical and experimental evidence on the role of DPP-1, DPP-4, DPP-9, and DPP-10 in pulmonary diseases." (PMID 42193335, 2026).
squamous cell carcinoma (1 paper, 2025). A carcinoma arising from squamous epithelial cells. "Tier 2 proteins, supported by transcriptomic evidence but not sensitivity analyses, included AGRN, ITGB2, SEPTIN3 (adenocarcinoma) and DPP10 (squamous cell carcinoma)." (PMID 41340014, 2025). "Additionally, we found that DPP10 (Log2FC = 1.08, pFDR = 0.007) and GP1BA (Log2FC = −1.21, pfdr = 1.24 × 10−11) exhibited significantly different expression between squamous cell carcinoma and normal tissues." (PMID 41340014, 2025).
Stillbirth (1 paper, 2017). Death of the fetus in utero after at least 22 weeks of gestation. "The clinical outcomes of these 14 pregnancies included one stillbirth and three terminations of pregnancies, which included two of the three cases with both trisomy 21 and DPP10 duplication." (PMID 28670437, 2017).